TPD52 (tumor protein D52)
Diseases named in the same sentence as TPD52 in open-access papers (continued):
Sharing a sentence is not in itself a finding about the gene and the disease.
lung carcinoma (8 papers, 2008 to 2025). "By reducing TPD52 expression, the androgen receptor inhibits the invasion of lung cancer and boosts the cisplatin response." (PMID 39757112, 2025). "Overall, AR plays an important role in suppressing lung cancer progression by altering the circ-SLCO1B7/TPD52 signaling axis." (PMID 37564195, 2023). "The in vivo data also validated the functional contribution of AR/circ-SLCO1B7/miR-139-5p/TPD52 axis to lung cancer progression." (PMID 37564195, 2023). "Through our analysis of the TCGA database, we observed a potential tumor-promoting role of TPD52 in lung cancer." (PMID 37564195, 2023). "The decreased expression of circ-SLCO1B7 alleviates its sponge as miR-139-5p, allowing miR-139-5p to suppress TPD52 messenger RNA and leading to the retarded lung cancer progression." (PMID 37564195, 2023). "On the other hand, the expression of TPD52 is downregulated in some cancers, such as papillary renal cell cancer, lung cancer, and liposarcoma." (PMID 35047407, 2021). "On the other hand, the expression of TPD52 is also downregulated in other cancer types such as leiomyosarcoma, papillary renal cell cancer, clear cell renal cell cancer, lung cancer, and liposarcoma." (PMID 35047407, 2021). "A recent study has reported two new miR-145 targets, namely, the metastasis gene FSCN1, which is regulated in nasopharyngeal carcinoma cell line invasion and metastasis and c-Myc, and TPD52, which is regulated in brain metastasis of lung cancer." (PMID 26657507, 2016). "First, we observed that lung cancer patients with lower TPD52 expression had higher survival rate." (PMID 37564195, 2023). "Additionally, miR-139-5p levels were gradually decreased as lung cancer progresses to high grade or stage, whereas TPD52 expression showed an opposite trend." (PMID 37564195, 2023). "Similarly to the effect of miR-145-5p, selective knockdown of OCT-4, EGFR, MYC, MUC-1 and the newly identified TPD52 impaired migration of lung cancer cells." (PMID 26440147, 2015). "Interestingly, TPD52 protein expression was increased in matched brain metastasis, when compared to both normal lung and primary lung cancer tissues." (PMID 26440147, 2015). "In our study, we confirmed that TPD52 indeed acts as an oncogene and is regulated by the AR/circ-SLCO1B7/miR-139-5p signaling pathway, promoting lung cancer progression." (PMID 37564195, 2023). "Collectively, the results from our study suggest that AR can suppress lung cancer cell invasion and increase DDP response by modulating the circ-SLCO1B7/miR-139-5p/TPD52 signaling pathway." (PMID 37564195, 2023). "Restoration of miR-145-5p expression using either vorinostat or 5-azacytidine, which released methylation of the miR-145 locus, led to inhibition of migration of lung cancer cells and to down-regulation of OCT-4, MYC, EGFR, MUC-1 and TPD52 expression." (PMID 26440147, 2015). "Therefore, we decided to focus on TPD52 for further investigation regarding its potential links to AR, circ-SLCO1B7 and miR-139-5p in lung cancer progression." (PMID 37564195, 2023). "However, our data also indicated that the reversal of AR regulated TPD52 expression by miR-139-5p was only partial, suggesting that sponging miR-139-5p is just one of the signaling pathways involved in the AR-circ-SLCO1B7-mediated lung cancer progression." (PMID 37564195, 2023). "Of interest, the three tumor-related genes: tumor protein D52, melanoma antigen family D 4, stathmin 1/oncoprotein 18 and two oncogenes DEK oncogene and forkhead box G1 were upregulated which has not been described in the context of lung cancer so far." (PMID 18992152, 2008).
colorectal cancer (6 papers, 2014 to 2025). A primary or metastatic malignant neoplasm that affects the colon or rectum. "Further, the role of TPD52 expression in cell migration and invation of colorectal cancer and underlying molecular mechanism was established." (PMID 28562687, 2017). "In the present study, we investigated the expression of MAL2 and TPD52 in colorectal cancer clinical specimens and the potential clinical significance." (PMID 28562687, 2017). "However, TPD52, an oncogene in this gene family, is strongly expressed in ovarian cancer, colorectal cancer, pancreatic cancer, and other malignancies but is expressed at low levels in hepatocellular carcinoma and leiomyosarcoma." (PMID 40973691, 2025). "In colorectal cancer, elevated TPD52 expression independently predicts poor survival and is associated with advanced tumor stage, metastasis, and enhanced invasiveness via Focal adhesion kinase (FAK)/integrin and PI3K/AKT-mediated EMT activation, positioning it as a potential therapeutic target." (PMID 40973691, 2025). "However, whether TPD52 regulates cellular motility in colorectal cancer is still unknown." (PMID 28562687, 2017). "However, the clinical significance of TPD52 overexpression in colorectal cancer has not been investigated." (PMID 28562687, 2017).
hepatocellular carcinoma (5 papers, 2015 to 2024). A malignant tumor that arises from hepatocytes. "Finally, the tumor protein D52 (Tpd52) is a potential suppressor of hepatocellular carcinoma." (PMID 29494634, 2018).
gastric cancer (4 papers, 2022 to 2025). A primary or metastatic malignant neoplasm involving the stomach. "Overexpression & prognosis: TPD52/TPD52L2 are overexpressed in gastric cancer (GC) and are correlated with advanced TNM stages and poor survival." (PMID 40973691, 2025). "Taken together, these collective results establish TPD52/TPD52L2 as critical regulators of GC cell proliferation in vitro, suggesting their potential as therapeutic targets for gastric cancer intervention​." (PMID 40973691, 2025).
glioma (4 papers, 2021 to 2024). A benign or malignant brain and spinal cord tumor that arises from glial cells (astrocytes, oligodendrocytes, ependymal cells). "TPD52, exclusively identified in the R_T0 saliva, was reported as upregulated in the human plasma of high-grade glioma patients and associated with a secondary metastatic group of patients; it should instead be further investigated as a potential biomarker of recurrence." (PMID 39684695, 2024). "Expression analysis of TPD52, KLF14, miR-124, and PKCε provided useful information on the differences existing between the normal brain and SOL, in addition to gliomas; thus, might prove to be useful having diagnostic or prognostic value." (PMID 35577881, 2022). "Similarly, ferritin heavy polypeptide 1 pseudogene 3 was reported to be upregulated in glioma and promoted glioma cell proliferation via the downstream mechanism of the miR-224-5p/TPD52 axis." (PMID 34108621, 2021). "It has been proven that the FTH1P3/miR-224-5p/TPD52 axis is responsible for glioma progression." (PMID 34947885, 2021).
melanoma (4 papers, 2013 to 2023). A malignant, usually aggressive tumor composed of atypical, neoplastic melanocytes. "Increased expression levels of TPD52 are associated with multiple types of cancers, including breast, prostate, pancreas, and melanoma." (PMID 37833790, 2023). "This is consistent with earlier findings demonstrating elevated expression of TPD52 in several cancer types, including breast, pancreatic, multiple myeloma, prostate, Burkitt’s lymphoma, and melanoma." (PMID 37833790, 2023). "The expression of TPD52 is upregulated in certain types of cancers, such as breast, prostate, ovarian, and pancreatic cancer, Burkitt’s lymphoma, multiple myeloma, and melanoma." (PMID 35047407, 2021). "Various studies reported the upregulation of TPD52 expression in quite a few cancers, such as breast, prostate, and pancreatic cancer, Burkitt’s lymphoma, multiple myeloma, and melanoma." (PMID 35047407, 2021). "PAX3-mediated regulation of melanoma cell survival and proliferation is through BCL2L1 and PTEN, and TPD52 (tumor protein D52) respectively." (PMID 24069584, 2013).
oral squamous cell carcinoma (4 papers, 2017 to 2024). "The balance between TPD52 and TPD54 expression plays an important role in high-malignant oral squamous cell carcinoma (OSCC) cells." (PMID 39767632, 2024). "Tumor protein D52 (TPD52) reportedly plays an important role in the proliferation and metastasis of various cancer cells, including oral squamous cell carcinoma (OSCC), and it is expressed strongly at the hypoxic center of the tumor and is involved in cell death resistance." (PMID 35887183, 2022). "Tumor protein D52 (TPD52) reportedly plays an important role in the proliferation and metastasis of various cancer cells, including oral squamous cell carcinoma (OSCC) cells, and is expressed strongly at the center of the tumor, where the microenvironment is hypoxic." (PMID 34217360, 2021).
brain tumor (3 papers, 2016 to 2022). "The value for TPD52 and PKCε also depicted their significance in predicting the brain tumor risk (AUC 0.62 and 0.56, respectively)." (PMID 35577881, 2022). "Our study indicated for following potential targetable biomarker, TPD52 which overexpression were noted in many cancer types including brain tumors." (PMID 31170943, 2019). "Recent study indicated that miR-145-5p and its target gene TPD52 contributed to malignancy progression and in metastasis of brain tumor." (PMID 27765924, 2016). "Taken together, TPD52 may be a potential biomarker and effective target to improve therapeutic strategies for better treatment of brain tumour." (PMID 35577881, 2022). "Studies delineating TPD52, KLF14 and PKCε expression in brain tumours and space occupying lesions (SOL) of brain are also scarce." (PMID 35577881, 2022).
pancreatic cancer (3 papers, 2021 to 2025). "TPD52 is expressed at a high level whereas miR-133a at a low level in pancreatic cancer tissues, both of which together with low differentiation of pancreatic cancer and III-IV stage of TNM constitute independent risk factors affecting the surgical prognosis of patients with pancreatic cancer." (PMID 38544991, 2024). "Prior studies established that TPD52 overexpression in pancreatic cancer drives tumor progression, where genetic suppression attenuated malignant phenotypes and xenograft growth through AKT inactivation." (PMID 40973691, 2025). "The high expression rate of TPD52 and the low expression rate of miR-133a in pancreatic cancer tissues were higher than those in normal paracancerous tissues (P<0.05), Table-I." (PMID 38544991, 2024). "TPD52 is expressed at a high level whereas miR-133a at a low level in pancreatic cancer tissues, both of which are related to the low differentiation, TNM III-IV stage and short survival time of patients with pancreatic cancer." (PMID 38544991, 2024). "Monitoring the expression levels of TPD52 and miR-133a in postoperative tissue samples is conducive to making a more accurate judgment on the prognosis of patients with pancreatic cancer." (PMID 38544991, 2024). "The relationship between the expression levels of TPD52 and miR-133a and the clinicopathological features of patients with pancreatic cancer was analyzed." (PMID 38544991, 2024). "The high expression rate of TPD52 and the low expression rate of miR-133a in pancreatic cancer tissues were higher than those in normal paracancerous tissues(P<0.05)." (PMID 38544991, 2024). "In this study, the expression levels of TPD52 and miR-133a in tissue samples of patients with pancreatic cancer were detected to investigate the value of TPD 52 and Mir-133a in evaluating the prognosis of pancreatic cancer surgery." (PMID 38544991, 2024). "Cox regression analysis showed that low differentiation of pancreatic cancer, III-IV stage of TNM, high expression of TPD52, as well as low expression of miR-133a were independent risk factors for postoperative survival of patients with pancreatic cancer (P<0.05), as shown in Table-IV." (PMID 38544991, 2024). "Moreover, multivariate Cox regression analysis showed that low differentiation of pancreatic cancer, III-IV stage of TNM, high expression of TPD52, as well as low expression of miR-133a were independent risk factors for postoperative survival of patients with pancreatic cancer(P<0.05)." (PMID 38544991, 2024).
renal cell carcinoma (3 papers, 2017 to 2025). "Conversely, renal cell carcinoma shows paradoxical tumor-suppressive activity; TPD52 downregulation is correlated with disease progression, while its restoration inhibits proliferation, EMT, and xenograft growth through PI3K/AKT pathway modulation." (PMID 40973691, 2025). "Moreover, the elevated expression level of TPD52 noticeably inhibited the proliferation, migration, and invasion of renal cell carcinoma cells, as well as decreased tumor progression in renal carcinoma xenografts." (PMID 35087592, 2022).
Breast invasive carcinoma (2 papers, 2021 to 2023). "Amplification of TPD52 and TPD54 was seen in a range of cancers including breast invasive carcinoma, ovarian and uterine cancers, and cancers of the colon and liver." (PMID 34287617, 2021). "To determine whether TPD52 expression correlates with patient outcome, we analyzed the overall survival (OS) with a TCGA‐BRCA cohort of 1109 Breast invasive carcinoma samples." (PMID 35666017, 2023).
breast tumors (2 papers, 2010 to 2020). "Amongst these were 4 extensively studied splicing isoforms (MYO6, TPD52, IQCG, and ACOX2) identified to be amongst the 5 most important isoforms differentially expressed between ER+HER2− and ER-HER2 primary breast tumors." (PMID 33050927, 2020).
cervical cancer (2 papers, 2021). A primary or metastatic malignant neoplasm involving the cervix. "In this study, we observed a significantly increased expression of TPD52 (23.8 ± 0.42) in understudied samples of cervical cancer compared to the controls." (PMID 35047407, 2021). "In the present study, we observed an association of the expressions of TPD52, KLF9, miR-223, and PKCε with tumor stage, metastasis, and treatment status of cervical cancer patients." (PMID 35047407, 2021). "Hence, TPD52 may serve as a potent early diagnostic biomarker in cervical cancer." (PMID 35047407, 2021). "We observed an increased expression of TPD52 in cervical cancer patients relative to healthy controls who have very low levels of the TPD52 gene in their blood." (PMID 35047407, 2021). "It has been reported that miR-15a-3p increased radiosensitivity in cervical cancer by targeting TPD52, suggesting that miR-15a-3p may be a potential therapeutic target." (PMID 34532284, 2021). "The relative expressions of TPD52, KLF9, miR-223, and PKCε in cervical cancer patients were measured with respect to their clinical features." (PMID 35047407, 2021). "In our study, we have measured the co-expressions of TPD52, KLF9, miR-223, and PKCε in cervical cancer." (PMID 35047407, 2021). "Relationship between TPD52, KLF9, PKCε, and miR-223 expression and clinicopathological features of cervical cancer." (PMID 35047407, 2021). "Hence, our study also aimed to identify the combined expression patterns of TPD52, KLF9, miR-223, and PKCε, and their relationship with clinicopathological features, and to investigate the diagnostic and prognostic value of these genes in cervical cancer patients." (PMID 35047407, 2021). "For verification of the relationship between these blood-based biomarkers (TPD52, KLF9, miR-223, and PKCε) and cervical cancer, ROC curves were generated." (PMID 35047407, 2021). "There was a 23-fold increase in TPD52 expression, a 2-fold increase in miR-223 expression, a 0.14-fold decrease in KLF9 expression, and a 0.05-fold decrease of PKCε expression in cervical cancer." (PMID 35047407, 2021). "In the current study, the co-expressions of tumor protein D52 (TPD52), KLF9, microRNA 223 (miR-223), and protein kinase C epsilon (PKCε) were evaluated in cervical cancer patients and a possible relation with disease outcome was revealed." (PMID 35047407, 2021). "The expressions of TPD52, KLF9, miR-223, and PKCε were studied in the blood of 100 cervical cancer patients and 100 healthy controls using real-time PCR." (PMID 35047407, 2021). "Moreover, upregulation of the expressions of TPD52 and miR-223 and downregulation of the expressions of KLF9 and PKCε were found in peripheral blood of cervical cancer patients." (PMID 35047407, 2021). "Elevated expressions of TPD52 and miR-223 and reduced expressions of KLF9 and PKCε in peripheral blood of cervical cancer patients may serve as predictors of disease diagnosis and prognosis." (PMID 35047407, 2021). "Overall, we found that the expressions of TPD52 and miR-223 were increased 23- and 2-fold in peripheral blood of cervical cancer patients, respectively, whereas expressions of KLF9 and PKCε were 0.14- and 0.05-fold reduced in cervical cancer patients relative to healthy individuals." (PMID 35047407, 2021).
liposarcoma (2 papers, 2021 to 2023). A usually painless malignant tumor that arises from adipose tissue. "However, TPD52 expression is also determined to be downregulated in few cancers, including lung, papillary renal cell, and liposarcoma." (PMID 37833790, 2023).
prostate (2 papers, 2014 to 2021). "Week to moderate expression of TPD52 was observed in tissue of benign prostate and strong protein expression was seen in clinically localized prostate samples and metastatic prostate cancer." (PMID 34099820, 2021).
serous carcinoma (2 papers, 2010 to 2017). "TPD52 expression in high-grade serous carcinoma was shown to be highand was associated with poor OS in CRC patients." (PMID 28562687, 2017). "MAL2 expression was highest in serous carcinomas relative to other histological subtypes, whereas TPD52 expression was highest in clear cell carcinomas." (PMID 20846453, 2010). "Like MAL2, TPD52 was overexpressed in high-grade serous carcinomas relative to borderline tumours, but was more equivalently expressed in high-grade serous tumours relative to the combined cohort of other histological subtypes." (PMID 20846453, 2010). "Statistical comparisons reproducibly highlighted that MAL2 staining was higher in high-grade serous carcinomas, whereas TPD52 was indicated to be more equivalently expressed." (PMID 20846453, 2010). "MAL2 and TPD52 were significantly overexpressed in high-grade serous carcinomas compared with serous borderline tumours." (PMID 20846453, 2010). "As MAL2 was most frequently overexpressed in serous carcinomas, we compared MAL2 and TPD52 staining in high-grade serous carcinomas versus all others." (PMID 20846453, 2010). "Dividing the stage III serous carcinoma cohort according to median MAL2 or TPD52 SPC tumour values indicated similar overall survival according to MAL2 staining, but a trend towards improved overall survival with increased TPD52 staining." (PMID 20846453, 2010).
triple-negative breast carcinoma (2 papers, 2021). An invasive breast carcinoma which is negative for expression of estrogen receptor (ER), progesterone receptor (PR), and human epidermal growth factor receptor 2 (HER2). "In triple-negative breast cancer, PCAT6 inhibition increases radiosensitivity of cancer cells through ceRNA pattern to regulating miR-185/TPD52 axis." (PMID 34277403, 2021).
acute lymphoblastic leukemia (1 paper, 2025). Leukemia with an acute onset, characterized by the presence of lymphoblasts in the bone marrow and the peripheral blood. "In particular, TPD52L2 may be a marker of acute lymphoblastic leukemia, and TPD52 and TPD52L2 are frequently coexpressed in childhood leukemia." (PMID 40973691, 2025).
asthma (1 paper, 2021). "rs12543811 is located between genes TPD52 and ZBTB10 and has moderate H3K27ac fold change values in asthma relevant cell types (mean percentile is 52th)." (PMID 34669738, 2021).
astrocytomas (1 paper, 2022). "Differential expression analysis of TPD52, PKCε, KLF14 and miRNA 124 in brain cancer subtypes: astrocytomas, glioblastomas, and oligodendrogliomas revealed that the expression of TPD52 and PKCε was up regulated in glioblastomas compared to astrocytomas and oligodendrogliomas." (PMID 35577881, 2022).